CAV1 (caveolin 1)
Diseases named in the same sentence as CAV1 in open-access papers (continued):
Sharing a sentence is not in itself a finding about the gene and the disease.
breast carcinoma (continued). "Our previous studies have proven that Cav-1 could suppress the glycolytic metabolism of breast cancer cells, and therefore represents a reliable target for glycolysis-related treatment strategies." (PMID 34568078, 2021). "Importantly, combination of the autophagy inhibitor HCQ with Doxo dramatically diminishes the superiority of the CAV1 KD tumors, suggesting a possible stratagem to overcome Doxo resistance in CAV1-downregulated breast cancer patients by targeting autophagy." (PMID 34786475, 2021). "Blockage of autophagy may be a possible solution for Doxo-resistant breast cancer patients with reduced CAV1 expression." (PMID 34786475, 2021). "Clinical studies have shown that CAV-1 is an important predictor of breast cancer prognosis." (PMID 33816265, 2021). "Here, SMLM network analysis quantitatively shows that expression of the CAV1 CSD F92A/V94A mutant in CRISPR/Cas CAV1 knockout MDA-MB-231 breast cancer cells reduces the size and volume and enhances the elongation of caveolae and scaffold domains, with more pronounced effects on S2 and S1B scaffolds." (PMID 33833286, 2021). "In various tumor entities such as breast cancer, gastric cancer, and prostate cancer, downregulation of Cav-1 protein expression in CAFs could be shown." (PMID 33774714, 2021). "Our previous studies have identified Cav-1 as a promising cancer suppressor protein as it could impair breast cancer growth and metastasis by impairing glycolytic metabolism." (PMID 34568078, 2021). "CAV1 loss in MMTV-PyVT mice could accelerate the tumorigenesis and increase the tumor multiplicity and burden of breast cancer." (PMID 34568078, 2021). "The mitochondrial-targeted superoxide dismutase 2(SOD2) is a potential inhibitor that can resist to oxidative stress and block the production of molecules that can nourish tumors, thereby effectively reversing the tumor-promoting phenotype of CAV-1 in breast cancer cells." (PMID 33816265, 2021). "Preclinical studies have proven that ADQ extract could chemosensitize breast cancer by directly attenuating caveolin-1 expression in mammary tumor cells." (PMID 34461944, 2021). "In terms of mechanisms, both immunofluorescence assay and western blotting assay validated that ursolic acid treatment significantly attenuated the expression levels of glycolysis-associated proteins (LDH-A and c-Myc) whereas increasing SP1 and Cav-1 expression levels in mammary tumor tissues." (PMID 34568078, 2021). "In addition, betulinic acid suppressed erobic glycolysis in breast cancer via Cav-1/NF-κB/c-Myc signaling." (PMID 33381039, 2020). "Lastly, the clinical implications of Cav-1 in breast cancer were analyzed." (PMID 32528105, 2020). "Moreover, caveolin-1 was found to be responsible for the formation of invadopedia and breast cancer metastasis in vivo mainly via the induction of PI3K-specific pathway." (PMID 33150941, 2020). "Interestingly, it is elevated in other malignancies such as endometrial carcinoma, hepatic cancer, breast cancer, prostate cancer, and pancreatic cancer, in which Cav-1 propels cell growth and migration and results in cancer deterioration." (PMID 31991790, 2020). "Previous studies have indicated that Cav-1 functions as a tumor suppressor and pro-apoptotic protein in the early transformation and development of several human cancer types including lung, colon, ovarian, breast cancer and osteosarcomas." (PMID 32117718, 2020). "Moreover, Cav-1 expression in MMTV-Wnt1 mice mammary-tumor tissues gradually decreased concomitantly with breast cancer progression." (PMID 32528105, 2020). "Altogether, Cav-1 predicts a better clinical outcome in breast cancer patients." (PMID 32528105, 2020). "The in vivo targeting ability of each nanoprobe was established by imaging mice bearing subcutaneous tumors expressing one of three biomarkers of relevance in breast cancer: caveolin 1 (CAV1), C-X-C chemokine receptor type 4 (CXCR4), and Folate Receptor alpha (FRα)." (PMID 33172421, 2020).
breast carcinoma (continued). "Notably, epithelial Cav-1 expression significantly correlated with a better overall survival and delayed onset age of breast cancer patients." (PMID 32528105, 2020). "Moreover, the correlation between epithelial Cav-1 expression and clinicopathological parameters of breast cancer patients was analyzed using a human breast cancer tissue microarray." (PMID 32528105, 2020). "Furthermore, Cav-1 knockdown significantly increased the CD44+/CD24−/low subpopulation in the breast cancer xenograft formed by the reinoculated BCSCs, whereas Cav-1 overexpression decreased this subpopulation." (PMID 32528105, 2020). "Similarly, mouse mammary-tumor tissues also exhibited reduced Cav-1 expression when compared with that of normal mammary tissues." (PMID 32528105, 2020). "Interestingly, Cav-1 can regulate cell apoptosis and autophagy at the same time through 17β-estradiol-mediating pathway in human breast cancer cell line, BT474." (PMID 31759347, 2019). "Further research is warranted to conclude whether the epithelial cell profile and cav-1 expression of the fat-1 mouse is protective against breast cancer." (PMID 31619022, 2019). "Finally, fibroblasts co-cultured with breast cancer cells displayed Caveolin-1 (CAV-1) downregulation and increased expression of markers for myofibroblasts." (PMID 31426364, 2019). "CAV1 also participates in breast cancer metastasis by suppressing this process." (PMID 31362353, 2019). "It has been reported that Caveolin-1 acts as a tumor suppressor in ovarian and breast cancers, and high expression of Caveolin-1 may correlate with favorable outcome of ovarian cancer." (PMID 31497537, 2019). "Expression of CAV1 in SUM149 cells (an inflammatory breast cancer model) increased the invasive potential of these cells via activation of the Akt1 pathway, which phosphorylates the RhoC GTPase, a key player in microtubule and microfilament regulation, to promote cell adhesion and migration." (PMID 31362353, 2019). "This study not only provides experimental evidence and molecular mechanisms that may facilitate the safe and effective therapeutic use of herbal medicines for breast cancer, and may lead to CAV1-based therapeutic strategies for mammary malignancies." (PMID 30333750, 2018). "Some authors hypothesize that dysfunction of regulation of the TGFβ / SMAD pathway by caveolin-1 (Cav-1) is involved in both the development of fibrosis and breast cancer." (PMID 30687318, 2018). "Dysregulation of tumor Cav-1 plays an important role in tumorigenesis of breast cancer." (PMID 30348118, 2018). "We suppose that breast cancer patients with higher tumor Cav-1 expression may transport more nab-paclitaxel into the breast cancer cells through transcytosis and show better efficacy with higher tumor intracellular concentrations of nab-paclitaxel." (PMID 30348118, 2018). "Conversely, downregulation of Cav-1 expression in stroma plays a tumor-promoting role and predicts early cancer recurrence, lymph node infiltration, and chemotherapeutic resistance almost in all subtypes of breast cancer." (PMID 30348118, 2018). "In previous studies, the first-line diabetes drug metformin, which can inhibit mitochondria ATP production through up-regulation of AMPK, was demonstrated to induce caveolin-1 expression in lung and breast cancer cells, and caveolin-1 is required for AMPK activity when metformin is applied." (PMID 29500444, 2018). "Furthermore, we reveal the pro-invasive consequences of targeted inhibition of FASN and ERα signalling in ERα-positive breast cancers and we provide evidence for the therapeutic potential of caveolin-1 in this specific context." (PMID 29331414, 2018). "The absence of stromal CAV1 in breast cancer was shown in numerous studies to be associated with early disease recurrence, advanced tumor stage and lymph node metastases, increased distant metastasis, and poor survival." (PMID 29850392, 2018).
breast carcinoma (continued). "Importantly, Methotrexate and Etoposide increased the mRNA and protein levels of CAV1 in colon and breast cancer cells." (PMID 29340103, 2017). "Here we show that pre-treatment with an inhibitor of the Src-family kinases (PP2) blocked the increase in cell migration and invasion in colon and breast cancer cells and that CAV1 silencing decreased particularly MMP9 activity induced by the anti-neoplastic drugs." (PMID 29340103, 2017). "Silencing of CAV1 in stroma stimulates tumor growth in a xenograft model of breast cancer." (PMID 29099748, 2017). "In an alternative tumor model, which was obtained by injecting E0771 breast cancer cells orthotopically in the mammary fat pad, lung metastases were significantly increased upon deletion of Cav1 in the BM, whereas primary tumor growth was similar between groups." (PMID 29212030, 2017). "Colon and breast cancer cells were identified where CAV1 levels were low due to epigenetic suppression and could be reverted by treatment with the methyltransferase inhibitor 5’-azacytidine." (PMID 29340103, 2017). "Here, we describe how Caveolin-1 (Cav1) in MAMs prevents metastatic growth in the E0771 orthotopic breast cancer model, the subcutaneous Lewis lung carcinoma (LLC) model and the genetically engineered polyoma middle T (MMTV-PyMT) spontaneous breast cancer model." (PMID 29212030, 2017). "In breast cancer, loss of stromal Cav-1 was identified as a predictive biomarker of early tumor recurrence, lymph node metastasis, and tamoxifen-resistance as well as decreased survival in human breast cancer patients, suggesting that Cav-1 functions as a tumor suppressor in breast cancer." (PMID 28546853, 2017). "CAV1 can inhibit the growth and metastasis of breast cancer." (PMID 29190968, 2017). "Furthermore, a significant influence of CpGI shore methylation on CAV1 in breast cancer was previously reported." (PMID 28155687, 2016). "The loss of stromal Cav-1, rather than epithelial Cav-1 expression, was an independent prognostic factor in breast cancer outcome." (PMID 26828520, 2016). "Moreover, rescue of Cav-1 expression in a breast cancer cell line (MCF7) suppressed Nrf2 and reduced MnSOD expression." (PMID 26543228, 2016). "Next, we determined whether Cav-1 expression is reduced in mammary tumors of genetically modified mice constitutively expressing activated c-neu (ErbB2) gene (FVB-MMTV-ErbB2)." (PMID 26543228, 2016). "On the opposite, the consequences of caveolin 1 deregulation has never been clearly studied in muscle, although the protein has been largely linked to several major diseases in other tissues: breast cancer, atherosclerosis...." (PMID 25799323, 2015). "In addition, eight (72.7%, 8/11) HER-2 positive breast cancer specimens had a higher caveolin-1 expression than normal tissues." (PMID 26172389, 2015). "In our study, a high level of caveolin-1 expression was noted in 68.8% of breast cancer specimens." (PMID 26172389, 2015). "In this study, the caveolin-1 expression pattern was examined in 32 breast cancer patients." (PMID 26172389, 2015). "It has also been suggested that the high expression of caveolin-1 in stromal cells has a protective effect against tumor progression in breast cancer and could be a good prognostic indicator." (PMID 26172389, 2015). "Treatment of breast cancer cell lines with 5-AZA successfully increases both CAV1 mRNA and protein." (PMID 26112043, 2015). "The authors highlight a negative correlation between the survival rate of estrogen receptor α (ERα)-positive breast cancer patients and CAV1 expression, suggesting that CAV1 CGI shore methylation could be used as a prognostic marker for this type of cancer." (PMID 26404381, 2015). "Overexpression of caveolin-1 in breast cancer predicts a good outcome." (PMID 26690480, 2015).
breast carcinoma (continued). "In our study, caveolin-1 expression varied in different breast cancer cell lines: triple negative MDA-MB-231 cells showed the greatest caveolin-1 expression, while HER-2 positive SKBR-3 and BT-474 cells showed relatively moderate and lower caveolin-1 expressions, respectively." (PMID 26172389, 2015). "Because CAV1 was suggested to favor cell proliferation in breast cancer cells, we evaluated whether alterations in CAV1 levels affected proliferation in Ishikawa and Hec-1A cells transduced with the shCav-1(#5) or shLuc contructs." (PMID 26054531, 2015). "The expression of caveolin-1 in HER-2 positive breast cancer cells could be a potential biomarker to predict the efficacy." (PMID 26172389, 2015). "Caveolin-1 has been demonstrated to have an oncogenic or tumor suppressor role in breast cancer." (PMID 26172389, 2015). "Caveolin-1 was shown to be expressed in 68% (22/32) of the breast cancer specimens." (PMID 26172389, 2015). "Cav-1 expression is significantly reduced in mammary tumors of c-ErbB2 transgenic mice." (PMID 26431273, 2015). "Therefore, in this study we set out to examine the role of caveolin-1 in modulating the contribution of BKCa channels to breast cancer cell proliferation and invasion." (PMID 25397596, 2014). "The functional complex of caveolin-1 and BKCa in the membrane microdomain may be served as a potential therapeutic target in breast cancer." (PMID 25397596, 2014). "Therefore, we determined the effects of caveolin-1 knockdown mediated up-regulation and activation of BKCa channel on breast cancer proliferation and invasion." (PMID 25397596, 2014). "We identified that caveolin-1 and BKCa were co-localized and could be reciprocally co-immunoprecipitated in human breast cancer MCF-7 cells." (PMID 25397596, 2014). "Furthermore, caveolin-1 expression levels are significantly lower in human breast cancer cells than in their normal mammary epithelial counterparts." (PMID 25397596, 2014). "The functional complex of caveolin-1 and BKCa may serve as a new therapeutic target in breast cancer." (PMID 25397596, 2014). "Recently, it has been reported an strong association between CAV1 and CAV2 expression and high histological grade, and lack of hormone receptors positivity (ER and PR) in basal-like breast cancer subtype, providing evidence that these proteins can have oncogenic properties." (PMID 24591761, 2014). "The present study indicated that caveolin-1 and BKCa channel were co-localized and could be reciprocally co-immunoprecipitated in human breast cancer MCF-7 cells." (PMID 25397596, 2014). "Furthermore, there are notable similarities between this network and that present in human basal and claudin-low breast cancer cell lines, including increased tyrosine phosphorylation of Met, Cav1, Bcar1 and Tln1." (PMID 25200860, 2014). "Moreover, a recent study in breast cancer cell lines also demonstrated the direct relation between the expression of Cav-1 gene and the methylation level of certain CpG-rich regions." (PMID 24751908, 2014). "Phosphorylation of CAV1 on Tyr-14 regulates paclitaxel-mediated apoptosis in MCF-7 breast cancer." (PMID 24997799, 2014). "Recent studies suggest that caveolin-1 inhibits breast cancer cell proliferation and invasion." (PMID 25397596, 2014). "Recently, high Cav1 cell expression, in association with an absence of Cav1 stromal expression, has been reported to be closely associated with poor outcome in a subset of breast cancer patients." (PMID 23521716, 2013). "CAV1 is an important component of caveolae membranes and loss of CAV1 in the fibroblast compartment, rather than within breast cancer tumour cells was shown to be an independent predictor of lymph node metastasis and poor outcome." (PMID 24229053, 2013). "Caveolin-1 down-regulation is found in human ovarian, lung and breast carcinomas." (PMID 23894397, 2013).
breast carcinoma (continued). "Further investigations are required to determine whether Cav-1 can be used as a marker and/or a therapeutic target for claudin-low breast cancers." (PMID 22356861, 2012). "In addition, overexpression of Cav-1 in human breast cancer cell lines inhibited proliferation and soft agar colony formation." (PMID 22356861, 2012). "Caveolin-1 is a well-established cancer marker for breast cancer prognostics." (PMID 22995409, 2012). "Overexpression of caveolin-1 in a PTRF/cavin-1 null breast cancer cell line, SK-BR-3 was recently reported to elicit formation of long tubules that may mediate signaling events different from caveolae." (PMID 22912783, 2012). "Most of the work performed on Cav-1 in breast cancer has been directed towards the stromal cells." (PMID 22356861, 2012). "Therefore, our study supports the findings that claudin-low mammary tumors express more Cav-1 than epithelial mammary tumors." (PMID 22356861, 2012). "Interestingly, tumors that recurred following IGF-IR downregulation in the mammary tumors acquired a claudin-low phenotype and genotype and expressed Cav-1 at significantly higher levels (~14-fold) than the initial mammary tumor." (PMID 22356861, 2012). "Therefore, our findings suggest that Cav-1 expression can be used to differentiate mammary tumors with epithelial characteristic from those with mesenchymal or more specifically, claudin-low characteristics." (PMID 22356861, 2012). "Western blotting and immunofluorescence for Cav-1 protein and qRT-PCR for Cav-1 mRNA revealed that tumor cells themselves can express Cav-1 and the claudin-low mammary tumor cell lines (RJ348 and RM11A) expressed higher levels of Cav-1 protein and mRNA than the epithelial tumor cell lines." (PMID 22356861, 2012). "However, it is also formally possible that the role of caveolae and caveolin-1 in modulating the diffusion of CTxB are different in adipocytes and mammary tumor cells than in MEFs." (PMID 22511973, 2012). "We found that mammary tumors induced by IGF-IR overexpression expressed low levels of caveolin-1 while mammary tumors that became independent of IGF-IR signalling expressed considerably higher levels of caveolin-1." (PMID 22356861, 2012). "Furthermore, they showed that ectopic expression of Caveolin-1 or knockdown of STAT3 reduces the invasive features of breast cancer cells in vitro and brain colonization in vivo." (PMID 22567347, 2011). "A P132L mutation in caveolin-1 confers a dominant-negative effect on invasiveness of human schirrhous breast cancers and upregulates genes involved in invasiveness and metastasis, including Rho-related signaling molecules and genes expressed by stem cells." (PMID 22093547, 2011). "Moreover, it has been shown that STAT3 inhibition by restoration of its inhibitor, suppressor of cytokine signalling (SOCS-1), results in induction of Caveolin-1, a tumour suppressor gene in breast cancer." (PMID 22567347, 2011). "We speculated that these Cav-1 (-/-) stromalgene profiles might also overlap with the transcriptional stromal profilesobtained from human breast cancers." (PMID 20442453, 2010). "Indeed, Cav-1 was found to be down-regulated in many types of cancers including breast cancer, colon cancer, lung cancer, ovarian cancer, sarcomas, and thyroid cancer." (PMID 20700465, 2010). "Intersection of Cav-1 (-/-) stromal proteomics with the human breast cancer stromal gene lists." (PMID 20442453, 2010). "In addition, overexpression of caveolin-1 in the MCF-7 breast cancer cell line has been shown to modulate EGFR activation levels and EGF-induced EGFR signaling." (PMID 19816600, 2009). "Also, the re-expression of caveolin-1 in the breast cancer cell lines MCF7 and ZR75 is sufficient to reduce proliferation and promote apoptosis, possibly by a mechanism involving down-regulation of survivin." (PMID 18400052, 2008).